AURKA (aurora kinase A)
Diseases named in the same sentence as AURKA in open-access papers (continued):
Sharing a sentence is not in itself a finding about the gene and the disease.
breast cancer (continued). "To validate our data in a cancer cell context, we examined the morphology of the mitochondrial network and its correlation to the levels of AURKA expression in four breast cancer cell lines." (PMID 30070631, 2018). "Kinase inhibitor screens in both endocrine-sensitive and endocrine-resistant cell lines identified AURKA as a potential treatment target in ER+ breast cancer." (PMID 29289986, 2018). "In luminal ER+ breast cancer models, activation of AURKA is required to induce EMT and clonal expansion of CD44+/CD24low/− cells, thus driving tumor progression." (PMID 29289986, 2018). "AURKA is located on chromosome 20q13, frequently amplified and overexpressed in human malignancies, involving breast cancer, pancreatic cancer, and gastric cancer." (PMID 30405856, 2018). "Remarkably, our data reveal a novel potential therapeutic strategy for targeting both the cytoplasmic and nuclear AURKA function to effectively eliminate BCSCs, so as to overcome both breast cancer and drug resistance." (PMID 28114286, 2017). "Aurora kinase A (AURKA), which is commonly amplified in a subset of cancers and has increased mRNA expression in breast cancers, has been recently shown to have kinase-independent activities." (PMID 28587062, 2017). "We further demonstrated that the AURKA and FOXM1 inhibitors can function synergistically to inhibit AURKA activity and disrupt the positive feedback loop to more effectively limit the tumorigenicity of breast cancer cells." (PMID 28114286, 2017). "AURKA overexpression has been demonstrated in various human cancers, including breast cancer, head and neck squamous cell carcinoma, colorectal cancer, ovarian cancer, and advanced OSCC." (PMID 28152093, 2017). "AKI603 inhibited AURKA activity in a small dose and overcome chemoresistance by targeting breast cancer initiating cells." (PMID 28592839, 2017). "In previous study, our group found that AURKA enhanced breast cancer cell migration by enhancing the dephosphorylation and activation of cofilin, which facilitated actin reorganization." (PMID 28592839, 2017). "In this manner, AURKA can act as a transcriptional regulator to induce MYC expression in human breast cancer cell lines." (PMID 28587062, 2017). "FBXW7 acts as a tumor suppressor involved in the degradation of substrates with oncogenic activity frequently overexpressed in breast cancer such as Cyclin E, c-Myc and AURKA." (PMID 27409838, 2016). "Surprisingly, a strong correlation between AurkA expression and β-catenin localization in breast cancer tissues suggested a link between AurkA and Wnt signaling." (PMID 27341528, 2016). "Our study shows a novel role for AurkA in maintaining Breast Cancer Initiating Cells (BCICs) through a pathway involving a Snail-miR-128-wnt3a/β-catenin axis as signaling mechanism (bottom picture)." (PMID 27341528, 2016). "While RAD21, BIRC5 and AURKA have already been recognised as important players in luminal breast cancers progression process, the remaining genes represent novel biomarkers and targets to explore." (PMID 27341628, 2016). "Further, it has also been shown that knock down of MUC16 in breast cancer cells resulted in a decrease of Cyclin B1 and activation of Aurora Kinase A levels." (PMID 27382435, 2016). "In our study, 70 % of the breast cancer patients had shown over expression in AURKA genes for tumor samples versus benign samples." (PMID 27454254, 2016). "Actually, we found that the CD44-positive subpopulation in primary breast cancer cells (KBr2, KBr3 and KBr4), showed higher levels of AurkA and wnt3a mRNAs as well as increased migratory ability, compared to CD44-negative cells." (PMID 27341528, 2016). "Our findings suggest a new role for AurkA, which proves to be able to control BCICs and, likely, aggressiveness of breast cancer." (PMID 27341528, 2016). "Remarkably, a strong correlation between AurkA and miR-128 expression in breast cancer tissues confirmed our findings." (PMID 27341528, 2016).
breast cancer (continued). "Noteworthy, we found that breast cancer samples showing increased levels of AurkA, lost cortical β-catenin." (PMID 27341528, 2016). "This molecular mechanism is strongly supported also by the strong correlation between AurkA expression and miR-128 levels in 81,25% (26 out 32) (P = 0.04295) of breast cancer patients." (PMID 27341528, 2016). "Several of these genes have been previously linked to tumourigenesis in breast cancer, including KDM5B, RAD21, BIRC5, AURKA and MSRA." (PMID 27341628, 2016). "We first examined cytoplasmic and nuclear expression of AURKA in breast cancer and adjacent normal tissues." (PMID 26782714, 2016). "Following on these observations, we further assessed the link between the AURKA-HMMR-TPX2-TUBG1 functional module and risk of breast cancer in BRCA1 or BRCA2 mutation carriers." (PMID 25830658, 2015). "More direct evidence of the inability of tamoxifen to inhibit ligand-independently activated ER was obtained in a study showing that Aurora kinase A upon phosphorylation of ER renders breast cancer cells less sensitive to treatment with tamoxifen." (PMID 25625755, 2015). "In agreement with this, we have shown that Aurora kinase A plays a major role for growth of tamoxifen-resistant breast cancer cell lines, and that inhibition of Aurora kinase A restores the sensitivity to tamoxifen treatment." (PMID 25625755, 2015). "Simon and Roychowdhury suggested the amplification of the Aurora A Kinase (AURKA) in prostate and breast cancer." (PMID 25623468, 2015). "The study of gene loci functionally related to HMMR suggests an association between variation in AURKA/CSTF1 and risk of breast cancer among BRCA2 mutation carriers." (PMID 25830658, 2015). "Aurora kinase A (AURKA) is a single gene predictor of proliferation within the ER+ subtype of breast cancer." (PMID 26460486, 2015). "In contrast, Haibe-Kains et. al. found that in breast cancer the prognostic value of AURKA expression was comparable to multi-gene models." (PMID 24465512, 2014). "Although AURKA gene amplification is a common genetic aberration in breast cancer 16, its role as a therapeutic target for breast cancers harbouring amplification of this locus remains to be fully established." (PMID 24395524, 2014). "In ductal breast cancer, we found a grade-dependent increase of AURKA expression (P > 10−3), while the variations of expression of MAP9 and PLK1 are not significant (P > 0.2)." (PMID 24876664, 2014). "High expression levels of AURKA indicate decreased survival in breast cancer patients and is currently an anticancer target." (PMID 24344117, 2013). "In breast cancer, multiple genes localized to 20q have been identified as oncogenes, including Aurora-A kinase (AURKA), ZNF217, UBE2C and TPX2." (PMID 24344117, 2013). "Known breast cancer susceptibility genes like TPX2, AURKA, TK1 and BIRC5 are among the top 7 global drivers (the other 3 top drivers are GINS2, COX4NB and NUP93)." (PMID 21806811, 2011). "AURKA lies within a region of human chromosome arm 20q13 that is amplified in breast cancer, as confirmed here." (PMID 21352579, 2011). "We also included the Aurora kinase A expression model, as this model was shown to predict breast cancer patient outcome with similar accuracies to many other feature selection techniques." (PMID 20813028, 2010). "Among the parameters with statistically significant correlation with disease outcome were tumor grade and aurora kinase A (AURKA) gene expression, a proliferation associated gene shown to be a powerful predictor of survival in breast cancer." (PMID 20459663, 2010). "The Aurora kinase A model was previously shown to have comparable predictive accuracy to several feature selection techniques at predicting breast cancer patient survival, and can be used to make comparisons between feature selection techniques." (PMID 20813028, 2010).
breast cancer (continued). "To this, we analyzed the expression of two of the genes belonging to the 20-gene signature, UBE2C and AURKA, using immunohistochemistry on tissue array samples from human cervical (n = 55) and breast cancer (n = 86)." (PMID 20630075, 2010). "Currently, the selective AURKA inhibitor alisertib is being investigated in clinical trials, either as monotherapy or in combination with fulvestrant, for patients with advanced endocrine-resistant breast cancer (NCT02860000)." (PMID 40949156, 2025). "Moreover, AURKA itself plays a significant role as a kinase that promotes breast cancer proliferation and metastasis of breast cancer cells." (PMID 40003882, 2025). "Furthermore, the BC-G4 in the promoter of AURKA is enriched with multiple TF–TF interactions suggesting the vigorous activity of this G4 region in breast cancer." (PMID 40725120, 2025). "Therefore, recognizing HMMR as a promising therapeutic target, the study validates the overexpression of HMMR in breast cancer and various pan cancers and its correlation with certain proteins such as AURKA, TPX2, and CDK1 through online databases." (PMID 38576486, 2024). "Consequently, interference with AURKA leads to an increase in hormone receptors and enhances the sensitivity of breast cancer cells to endocrine therapy." (PMID 38995006, 2024). "Aurora kinase A (AURKA) is reported to be overexpressed in breast cancer." (PMID 39198859, 2024). "Our findings point to AURKA as a biomarker relevant for young breast cancer patients." (PMID 39198859, 2024). "To further demonstrate whether the Asp132-cleavage of AURKA is cell-type dependent, we measured cleavage in various types of cancer cells, including cervical cancer cells (HeLa), breast cancer cells (MDA-MB-231), and liver cancer cells (SMMC-7721 and HLE)." (PMID 38994036, 2024). "Thus, we provide new insights regarding the prognostic significance of Aurora-A/AURKA within young breast cancer patients." (PMID 39198859, 2024). "Furthermore, decreased MUC16 expression results in an accumulation of breast cancer cells at the G2/M phase of the cell cycle via Cyclin B1 and phosphorylation of AURKA, which in turn leads to apoptosis of breast cancer cells through JNK signaling." (PMID 39149564, 2024). "To determine if Asp132-cleavage of AURKA is triggered by other apoptotic stimuli, we induced apoptosis with a common chemotherapeutic drug paclitaxel (Taxol) in different cancer cell lines, including primary effusion lymphoma, cervical, and breast cancers." (PMID 38994036, 2024). "Moreover, in breast cancer, AURKA has been reported to outperform the proliferation marker Ki67 as a prognostic marker." (PMID 39198859, 2024). "In addition, we observed that 40 and 10 breast cancer cell-lines samples show the highest connectivity loss score of KIF11 and AURKA, respectively." (PMID 38622359, 2024). "This suggests that even though these EMT transcription factors are highly dysregulated in breast cancer, targeting a more upstream protein such as AURKA might suppress progression to metastasis." (PMID 38886738, 2024). "AURKA promotes distant metastases in ERα-positive breast cancer cells and its overexpression is strongly linked to decreased survival, high nuclear grade, and elevated HER-2/neu and progesterone receptor levels in breast cancer." (PMID 39334449, 2024). "Moreover, AURKA is closely related to disease recurrence in obese patients with early-stage breast cancer, while AURKAhigh in patients with gastric cancer has been linked to a higher risk of death." (PMID 38903715, 2024).
breast cancer (continued). "The amplification of the mitotic kinase AURKA has been identified in 11 out of 41 HR+ breast cancer biopsies from tumors resistant to CDK4/6 inhibitors, including examples of both intrinsic and acquired resistance, with no alterations detected in sensitive samples." (PMID 36900131, 2023). "In breast cancer, the serine/threonine kinase AURKA is typically overexpressed." (PMID 37711177, 2023). "Furthermore, RT-qPCR analysis of normal and TNBC patient cDNAs from Origene Breast Cancer cDNA array IV (BCRT504) also showed higher AURKA SLR in TNBC samples compared to normal." (PMID 37384380, 2023). "AURKA mRNA expression levels were higher in breast cancer tissues than in normal tissues." (PMID 37415951, 2023). "For example, AURKA activates the Cofilin-F-Actin pathway leading to breast cancer metastases." (PMID 37384380, 2023). "Our present observation could be of potential clinical relevance given the existence of several AURKA inhibitors that are currently being tested in patients with breast cancer (NCT02187991, phase 2 with alisertib, and NCT02134067, phase 1 with TAS-119)." (PMID 36717329, 2023). "Interestingly, TACC1 can form a complex with aurora kinase A, which controls translation and cell division in breast cancer." (PMID 37370789, 2023). "A role of nuclear AurkA in activation of hypoxia transcriptional programs has been also recently reported in breast cancer, a condition that drives cell migration, morphological changes, and increased stemness, thus determining dissemination and metastases at other organs." (PMID 36797043, 2023). "The effect of the small molecule inhibitors JNJ-165 and PHA-680632 on AURKA nuclear translocation in breast cancer cells was examined by immunofluorescence assays, which showed that the two inhibitors promoted the cytoplasmic accumulation of AURKA in MCF-7 cells." (PMID 37415951, 2023). "AURKA is a prognostic marker in obese patients with early breast cancer." (PMID 36232337, 2022). "They suggest that MDA-MB-231 breast cancer cells tend to splice AURKA pre-mRNA in a way to skip exon III, arguing that exon III might provide a protective function against tumorigenesis." (PMID 36067794, 2022). "Interestingly, many cases of miRNA targeting seem to be relevant particularly in those cancers for which AURKA overexpression is considered a promoting factor and a marker of poor prognosis, such as breast cancer, HCC and lung cancer." (PMID 36067794, 2022). "Basal‐line breast cancer exhibits AURKA gene amplification and elevated mRNA expression." (PMID 34981672, 2022). "Opposite effects have been reported for cell migration and metastasis of various cancers such as papillary thyroid and breast cancer, where overexpressed AURKA induced an up-regulation of SSH-1 expression, thus favoring the dephosphorylation and activation of CFL1." (PMID 35054947, 2022). "In addition, it has been reported that AURKA overexpression mediates resistance to PI3K-AKT-mTOR pathway inhibitors in breast cancer." (PMID 36471438, 2022). "Moreover, it has been demonstrated that AURORA kinase A, AURKA, sustains mTOR phosphorylation levels in PIK3CA-mutated breast cancer cells treated with a pan-PI3K inhibitor or the AKT inhibitor MK-2206." (PMID 33809714, 2021). "In addition, studies have reported that AURKA from the serine/threonine kinase family was overexpressed in various cancers and can be used as a prognostic marker for breast cancer and advanced serous ovarian cancer." (PMID 34565287, 2021). "Moreover, AURKA expression was also necessary to induce the expression of CD44 breast cancer stem-like cells marker." (PMID 33674749, 2021). "Moreover, the upregulation of AURKA inclined chemoresistance in breast cancer and ovarian cancer cells." (PMID 32978717, 2021). "Moreover, in breast cancer, the cancer cell proliferation is enhanced by AURKA via regulating ERK1/2." (PMID 34565287, 2021).
breast cancer (continued). "Furthermore, these findings are in agreement with our previous studies that showed the central role of AURKA in conferring to breast cancer cells a chemoresistant phenotype." (PMID 33674749, 2021). "Moreover, we observed that high grade breast cancer patients and lung adenocarcinoma patients with a high AURKA and NEK2 gene expression had a significant poor overall survival." (PMID 32033228, 2020). "Interestingly, studies have also found that the Phe allelic variation in AURKA rs2273535 appears to prevent breast cancer in Malaysian Chinese." (PMID 31636670, 2019). "Other studies on Triple-Negative Breast Cancer cases have to be performed to assess whether AURKA overexpression/amplification could predict the “PARPi and irradiation” sensitivity regardless of the proliferation/stem-cell like status and the BRCA-status." (PMID 31888054, 2019). "Quantitative analysis of transcript abundance among the three sub-populations of OR genes confirmed that the genes associated with breast cancer cell proliferation (MKI67, AURKA, BIRC5, CCNB1, MYBL2) were significantly abundant in sub-population I with OR2B6 upregulation." (PMID 31551495, 2019). "AURKA overexpression occurs in over 90% of breast carcinomas." (PMID 31254157, 2019). "Thus, this novel function of AURKA has untapped potential as a biomarker and therapeutic target for endocrine-resistant breast cancer." (PMID 29289986, 2018). "Moreover, in women with operable ER+ breast cancer treated with tamoxifen, both disease-free and overall survival (OS) were shorter among those with high levels of tumor expression of AURKA." (PMID 29289986, 2018). "The AURKA plays a role as a regulator of cellular mobility in breast cancer, therefore, drugs that act on this target may decrease metastasis." (PMID 30104527, 2018). "In addition, it was reported that BT549, MCF-7, MCF-10A, and MDA-MB-231 breast cancer cells when treated with AURKA inhibitor (ZM447439) showed low metastasis potential mediated by the inhibition of cell migration." (PMID 30104527, 2018). "In Malaysian Chinese, AURKA rs2273535 protected against breast cancer." (PMID 29678897, 2018). "For breast cancer, we investigated the performance of our predictor relative to a univariate model using the expression of the AURKA gene as covariate, since this model serves as a robust benchmark for other breast cancer predictors, and two validated gene signature-based predictors." (PMID 28333954, 2017). "Moreover, our study suggests AurkA/miR-128/Wnt3a axys as a druggable target to inhibit chemoresistance and recurrence in breast cancer." (PMID 27341528, 2016). "Altogether those findings strongly suggested that AurkA may control self-renewal and invasive capacity of BCICs, contributing to a worse outcome in breast cancer patients." (PMID 27341528, 2016). "Furthermore, we performed co-IP using breast cancer tissues, which displayed different levels of nuclear/cytoplasmic AURKA expression." (PMID 26782714, 2016). "Interestingly, we found that breast cancer samples, overexpressing AurkA (>1.5 fold-change in comparison with normal breast), similarly showed increased levels of CD44 as revealed by Q-PCR." (PMID 27341528, 2016). "This correlated expression was found in 26 out 32 breast cancers (75% + 6.25% = 81.25%) supporting the hypothesis of AurkA-miR-128-Wnt3a/β-catenin signaling also in clinical specimens." (PMID 27341528, 2016). "To verify this hypothesis, we modulated AurkA expression in breast cancer cell lines and evaluated the effects on BCICs." (PMID 27341528, 2016). "In contrast, AURKA was also highly expressed in the nuclear fraction of breast cancer tissue." (PMID 26782714, 2016). "To assess if AurkA may promote a more aggressive phenotype in vivo, we isolated primary breast cancer cells (named KBr1, KBr2, KBr3 and KBr4) from 4 different mastectomized breast cancer patients and injected them into immune-compromised mice." (PMID 27341528, 2016).